KALRN (kalirin RhoGEF kinase)
Description:
Promotes the exchange of GDP by GTP. Activates specific Rho GTPase family members, thereby inducing various signaling mechanisms that regulate neuronal shape, growth, and plasticity, through their effects on the actin cytoskeleton. Induces lamellipodia independent of its GEF activity.
Synonyms: DUET; DUO; HAPIP; TRAD; Hs.8004; Kalirin; ARHGEF24; KALNC2; CHDS5
Tractability: Small molecule: a structure with a bound ligand is known; it belongs to a druggable protein family. PROTAC: its protein half-life has been measured.
Gene: Protein-coding gene on chromosome 3 (124,033,369 to 124,726,325, forward strand). Ensembl gene ENSG00000160145.
Subcellular location: Cytoplasm; Cytoplasm, cytoskeleton
Subcellular location (Human Protein Atlas): Cytosol; Nucleoplasm
Pathways (Reactome):
Signal Transduction: G alpha (12/13) signalling events; G alpha (q) signalling events; MAPK6/MAPK4 signaling; NRAGE signals death through JNK; RAC1 GTPase cycle; RHOA GTPase cycle; RHOG GTPase cycle
Developmental Biology: EPHB-mediated forward signaling
Gene Ontology:
Molecular function: guanyl-nucleotide exchange factor activity; protein binding; protein serine/threonine kinase activity; ATP binding; protein kinase activity; protein serine kinase activity
Biological process: axon guidance; ephrin receptor signaling pathway; intracellular signal transduction; nervous system development; protein phosphorylation; regulation of small GTPase mediated signal transduction; signal transduction; vesicle-mediated transport
Cellular component: extracellular exosome; actin cytoskeleton; cytoplasm; cytosol; extrinsic component of membrane; postsynaptic density; cytoskeleton
Genetic constraint (gnomAD): Loss-of-function variants: 55 observed, 298.66 expected, observed/expected ratio (o/e) 0.18, 90% interval 0.15 to 0.23. The upper end of that interval is the gene's LOEUF score, 0.23, which puts it in group 1 of 6, group 1 being the genes least tolerant of losing a copy. Missense variants: 2,630 observed, 3,653.6 expected, observed/expected ratio (o/e) 0.72, 90% interval 0.7 to 0.74. Synonymous variants: 1,320 observed, 1,421.7 expected, observed/expected ratio (o/e) 0.93, 90% interval 0.89 to 0.97.
Homologues: Orthologues: macaque KALRN (99% identical), chimpanzee KALRN (99% identical), guinea pig KALRN (97% identical), rabbit KALRN (97% identical), mouse Kalrn (97% identical), dog KALRN (95% identical), tropical clawed frog kalrn (80% identical), zebrafish kalrna (66% identical), rat Kalrn (55% identical), zebrafish kalrnb (13% identical). Paralogues in human: TRIO (66% identical), PLEKHG4B (9% identical), MCF2L (9% identical), ARHGEF40 (9% identical), ARHGEF25 (8% identical), PLEKHG4 (8% identical), TIAM2 (8% identical), MCF2 (7% identical), TIAM1 (7% identical), MCF2L2 (7% identical), SPATA13 (6% identical), KIAA1755 (5% identical), and 10 more.